PGR (progesterone receptor)
Diseases named in the same sentence as PGR in open-access papers (continued):
Sharing a sentence is not in itself a finding about the gene and the disease.
breast cancer (continued). "Most breast cancers co-express estrogen receptor α (ERα) and progesterone receptor (PgR)." (PMID 34638241, 2021). "A significant advance has been achieved in determining treatment on the basis of subtypes of breast cancer, which are immunohistochemically classified based on the expression of oestrogen receptor (ER), progesterone receptor (PR) and human epidermal growth factor receptor 2 (HER2)." (PMID 34131308, 2021). "Based on the characteristics of molecular markers, breast cancer is divided into 3 major subtypes, namely estrogen receptor positive and progesterone receptor positive (luminal A, luminal B), HER2 overexpression (HER2+) and triple negative breast cancer (TNBC)." (PMID 34745969, 2021). "The American Society of Clinical Oncology and College of American Pathologists (ASCO/CAP) guidelines suggest that “Testing of DCIS for ER is recommended to determine potential benefit of endocrine therapies to reduce risk of future breast cancer, while testing DCIS for PgR is considered optional”." (PMID 33805352, 2021). "Four subtypes of breast cancer have been classified as: luminal A [estrogen receptor (ER)+ and/or progesterone receptor (PR)+ and human epidermal growth factor receptor-2 (Her2)-], luminal B (ER+ and/or PR+ and Her2+), Her2-enriched (ER−, PR−, and Her2+) and basal-like triple-negative breast cancer." (PMID 34746100, 2021). "Breast cancer has been also subtyped based on the molecular profile into four major groups based mainly on the expression status of hormone receptors; estrogen receptor (ER) and progesterone receptor (PR), and Her2/neu status." (PMID 34086748, 2021). "Furthermore, breast cancer has been categorized into five molecular subtypes based on immunohistochemical factors which include progesterone receptor (PR), estrogen receptor (ER), Ki67 proliferation index, and human epidermal growth factor receptor 2 (Her-2)." (PMID 34621407, 2021). "Moreover, the assessment of AGO2 expression profiles resulted in an improvement of prediction of the breast cancer subtype and estrogen receptor or progesterone receptor status by 15–20%." (PMID 33668654, 2021). "Approximately 70–80% of breast cancers are hormone-dependent; their growth is stimulated in response to the hormone estrogen, with the majority of these estrogen receptor positive (ER+) cancers also expressing the progesterone receptor (ER+/PR+ cancers)." (PMID 33671674, 2021). "The CG + GG genotype of XRCC6 rs2267437 was associated with an increased risk of estrogen receptor‐negative/progesterone receptor‐negative (ER−/PR−) breast cancer (CG + GG vs. CC: OR = 1.54, 95% CI = 1.12–2.13, p = 0.008) after Bonferroni correction." (PMID 33734613, 2021). "Breast cancers are heterogeneous and dynamic diseases classified into molecularly distinct subtypes based on the expression of estrogen receptor (ER), progesterone receptor (PR) and human epidermal growth factor receptor 2 (HER2), which influence the clinical outcomes and the therapeutic approaches." (PMID 33800302, 2021). "Over the past decades, the scientific developments led to a better understanding of breast cancer according to the expression of estrogen receptor (ER), progesterone receptor (PR), human epidermal growth factor receptor 2 (HER2) and proliferation marker (Ki-67)." (PMID 34001038, 2021). "PgR may also be localized along the plasma membrane of breast cancer cells, and the lymphocyte surface markers happen to be localized in the nucleus." (PMID 34203756, 2021). "Patients whose breast cancers express low levels of estrogen receptor (ER) or progesterone receptor (PgR) may be eligible for adjuvant endocrine therapy, but limited data are available to support this notion." (PMID 34638491, 2021).
breast cancer (continued). "Tumor and patient characteristics are classical factors that drive breast cancer therapy and predict prognosis together with the status of specific biomarkers, such as estrogen receptor (ER), progesterone receptor (PR) and human epidermal growth factor receptor 2 (HER2)." (PMID 33863935, 2021). "The current review summarizes current knowledge on the biology of ERα-positive PgR(−)negative breast cancer and discusses the associations between molecular mechanisms and clinical characteristics." (PMID 34638241, 2021). "To characterize the role of ENST00000508435 in breast cancers, we investigated the relationship between the expression of ENST00000508435 and some typical clinical pathologic parameters [tumor size, breast cancer biomarkers (ER, PgR, and HER2), lymph node metastasis, ki67 and Nottingham grade]." (PMID 34057025, 2021). "In addition to MCF7, another estrogen receptor- and progesterone receptor positive breast cancer cell line, T47D, was used for gene expression studies." (PMID 34356204, 2021). "Classification of breast cancer based on the clinical immunohistochemistry (IHC) status of estrogen receptor (ER), progesterone receptor (PR), and human epidermal growth factor receptor 2 (HER2) is fundamental in clinical subtyping, prognostication, and treatment selection." (PMID 33772089, 2021). "Primary diagnosis of breast cancer occurred in 44% (N = 8) of patients; 50% of these primary tumors were estrogen receptor (ER) positive, 25% were progesterone receptor (PR) positive, 25% were human epidermal growth factor receptor 2 (HER2) positive and 25% were triple negative." (PMID 34642329, 2021). "Breast cancer, a life-threatening disease that is among the most common cancers in women, is classified into subtypes according to the expression of estrogen receptor (ER), progesterone receptor (PR), and human epidermal growth factor receptor 2 (HER2)." (PMID 34407787, 2021). "BCSCs with CD44+/CD24−/low and ALDH1 phenotypes isolated from different subtypes of breast cancer, based on molecular profiling of receptor expression (estrogen receptor, progesterone receptor, or human epidermal growth factor receptor 2), have similar gene expression profiles." (PMID 33925129, 2021). "After comparing the HRs for BCSS and DFS in all subgroups using a multivariate analysis during a 5- and 10-year follow-up, our results suggested that higher ER or PgR expression level was associated with better 5-year BCSS and DFS among breast cancer patients received adjuvant hormone therapy." (PMID 33670083, 2021). "However, a quantitative/semi-quantitative histological evaluation instead of a qualitative assessment is considered superior when assessing other steroid receptors in breast cancer (ER and PgR) and thus was the natural choice of method for us." (PMID 34930399, 2021). "Clinically, BRCA1 variant carriers have a higher risk of developing triple-negative (TN) status in breast cancer, which is negative for ER, progesterone receptor (PgR), and HER2." (PMID 35008774, 2021). "Triple‐negative breast cancer (TNBC) is a heterogeneous subtype of breast cancer characterized by lack of expression of estrogen receptor (ER) and progesterone receptor (PR) and loss of human epidermal growth factor receptor 2 (HER2) gene amplification." (PMID 33207079, 2021). "We also analyzed the relationship between expression of FXR1 and clinical pathological parameters [tumor size, breast cancer biomarkers (ER, PgR and HER2), lymph node metastasis, ki67 and Nottingham grade], and found that the expression of FXR1 was positively correlated with lymph node metastasis." (PMID 34057025, 2021).
breast cancer (continued). "At present, prognostic and predictive biomarkers, such as human epidermal growth factor receptor 2 (HER2), estrogen receptor (ER), Ki-67, progesterone receptor (PR), and programmed death-ligand 1 (PD-L1), are validated for use in the decision-making over breast cancer therapies." (PMID 34227318, 2021). "Further studies should focus on breast cancers with discordantly expressed ER and PgR." (PMID 34638491, 2021). "Triple-negative breast cancer (TNBC) is the most lethal and aggressive subtype of breast cancer that lacks an estrogen receptor, the progesterone receptor and the human epidermal growth factor receptor 2 (HER2), making it unsuitable for hormonal- or HER2-based therapy." (PMID 33919653, 2021). "Progesterone receptor membrane component 1 (Pgrmc1) is a non-classical progesterone receptor associated with the development of the mammary gland and xenograft-induced breast cancer." (PMID 33832499, 2021). "It is difficult to make a general comparison with previous study, because of the different tumor model (spontaneous or orthotopic transplant), subtypes of breast cancer cells (estrogen receptor and progesterone receptor sensitivity and HER2 protein expression) and light/dark conditions." (PMID 33633796, 2021). "Inter-TH in breast cancer has led to the classification based on histology and expression profiles of the molecular markers; oestrogen receptor (ER), progesterone receptor (PR) and the overexpression or gene amplification of human epidermal growth factor receptor 2 (HER2)." (PMID 34934048, 2021). "Depending on hormone receptor and human epidermal growth factor type II receptor (HER2) oncoprotein expression, breast cancer (BC) is traditionally classified into luminal A or B (i.e., estrogen and/or progesterone receptor-positive), HER2-enriched, or triple-negative BC (TNBC)." (PMID 32719318, 2020). "In addition, we stratified breast cancer patients by molecular subtype [estrogen and progesterone receptor (ER/PR) and human epidermal growth factor receptor 2 (HER2/neu) status]." (PMID 33614510, 2020). "The median survival for patients with breast cancer and bone metastases is 65 months in the oestrogen/progesterone-receptor-positive (ER/PR-positive) groups, and 40 months in both the human epidermal growth factor receptor 2 (HER-2) positive and ‘triple-negative’ group." (PMID 32548731, 2020). "In contrast to non-pregnant counterparts, pregnancy-associated breast cancer is more likely to develop higher stage tumors, more poorly differentiated, and less common oestrogen or progesterone-receptor positivity." (PMID 33425755, 2020). "Hence, at this point, FFNP is the most advanced PET imaging agent for PgR in breast cancer patients, where it appears to have good selectivity for PgR (see Section 5.2)." (PMID 32718075, 2020). "Breast cancer tumors are dependent on estrogen and/or progesterone hormones for growth and this effect is mediated through estrogen receptor (ER) and progesterone receptor (PgR)." (PMID 33112549, 2020). "As a heterogeneous disease, breast cancer is clinically classified by taking into account the expression of estrogen receptor alpha (ERα), progesterone receptor (PR), and the presence/amplification status of the oncogenic human epidermal growth factor receptor 2 (HER2)." (PMID 32414394, 2020). "In Cyprus, approximately 9% of triple-negative (estrogen receptor-negative, progesterone receptor-negative, and human epidermal growth factor receptor 2-negative) breast cancer (TNBC) patients are positive for germline pathogenic variants (PVs) in BRCA1/2." (PMID 33120919, 2020). "Breast cancers were then classified into five subtypes based on the expression levels of estrogen receptor (ER), progesterone receptor (PgR), human epidermal growth factor receptor 2 (HER2), and Ki-67 in tumor cells, as determined by immunohistochemical and gene-expression analyses (St." (PMID 31372841, 2020).
breast cancer (continued). "Several biological factors including histological grade, human epidermal growth factor receptor 2 (HER2), estrogen receptor (ER), and progesterone receptor (PR) status have been identified and validated for their prognostic and predictive role in breast cancer." (PMID 32508053, 2020). "Breast cancer is a heterogeneous disease and is classified into different subtypes depending on the presence or absence of hormone receptors such as estrogen receptor (EsR), progesterone receptor (PR), and human epidermal growth factor receptor 2 (HER2)." (PMID 32397306, 2020). "In our study the breast cancer negative status of progesterone receptor was the determinant of high risk of recurrence, shorter TFFS and lack of response to treatment." (PMID 32235849, 2020). "Associations between BMI and breast cancer were stronger for estrogen receptor–positive (ER+) and/or progesterone receptor–positive (PR+) than for hormone receptor–negative (ER–) breast cancers." (PMID 32153503, 2020). "GR is a challenging target for PET imaging; however, because there are significant levels of GR in many breast cancers, we had concerns that GR binding by FFNP might confound PET imaging of PgR in breast cancer." (PMID 32718075, 2020). "Breast cancer is a heterogenous disease with multiple subtypes that display distinct risk factor patterns with differences between estrogen receptor (ER)/progesterone receptor (PR) positive (ER+PR+) versus those that are negative for ER/PR." (PMID 32468338, 2020). "Breast cancer can be classified according to three cellular markers: (i) progesterone receptor (PR) or estrogen receptor (ER) positive, (ii) human epidermal growth factor receptor-2 (HER2) positive, and PR and/or ER positive or negative, and (iii) triple negative breast cancer (TNBC)." (PMID 33374832, 2020). "Besides histological conservation, we also found the papillary carcinoma organoid keeping expression of the breast cancer biomarkers: estrogen receptor (ER), progesterone receptor (PR), human epidermal growth factor receptor (HER2), and antigen KI-67 (Ki67)." (PMID 32206037, 2020). "The majority of this research has been performed in breast cancer tissue on estrogen receptor, progesterone receptor, human epidermal growth factor receptor, Ki 67 assessment in breast cancer." (PMID 32334457, 2020). "The results suggest that the risk of death, disease progression or recurrence of breast cancer is modified by genetic variants of nuclear receptors (NR1/2, PGR), genes engaged in main metabolic pathway of doxorubicin (SLC22A16) and doxorubicin-progesterone-related gene (AKR1C3)." (PMID 32235849, 2020). "In total, 46.4% of the patients (n = 1062) had a HER2-positive, 22.8% (n = 522) a triple-negative, and 32.1% (n = 750) a luminal-A-like/luminal B-like primary breast cancer (defined as estrogen receptor (ER) and/or progesterone receptor (PR) positive, HER2-negative)." (PMID 32998430, 2020). "However, studies focused on ER+/PgR+ breast cancer indicate that miRNAs interact reciprocally with ER and PgR receptors." (PMID 32825530, 2020). "To lend support for this hypothesis, we performed immunohistochemistry staining of PGR and PGR_pS162 in a cohort of 361 breast cancer patients with known hormone-receptor status (PGR +/− and/or ER +/−)." (PMID 32686665, 2020). "In recent years, several tumor biomarkers have been identified that help to classify breast cancer into subgroups that have different prognoses and treatment: the estrogen receptor (ER), the progesterone receptor (PR) and the human epidermal growth factor receptor 2 (HER2)." (PMID 32610620, 2020). "Consequently, breast cancer biopsies have been routinely assayed for both ER and PgR for many years." (PMID 32718075, 2020). "Recent research indicates that some miRNAs may directly target and silence ER expression, e.g., miR-18a-5p and miR-222, and thus may participate in the development of ER(−)/PgR(+) breast cancer." (PMID 32825530, 2020).
breast cancer (continued). "These three breast cancer cell lines were also chosen as they span the spectrum of breast cancer cell receptor classifications, representing different levels of estrogen receptor (ER), progesterone receptor (PR) and HER2 positivity." (PMID 33142831, 2020). "Basal-like breast cancers are generally poorly differentiated tumors, are enriched in embryonic stem cell signatures, lack expression of estrogen receptor, progesterone receptor, and HER2 (triple-negative breast cancer), and show activation of proliferation-associated factors." (PMID 31934613, 2020). "Furthermore, ZNF471 expression was associated with progesterone receptor (PR), HER2, nodal status and tumor grade of breast cancer." (PMID 33203470, 2020). "Gene expression profiling enables the classification of breast cancer into distinct molecular subtypes with prognostic significance based upon histological grade and the status of estrogen receptor (ER), progesterone receptor (PgR), and HER2/neu expression (HER2 or ErbB2)." (PMID 32185126, 2020). "Breast cancer is a very heterogeneous disease, and its histological classification is mainly based on the expression of hormonal receptors such as estrogen receptor (ER), progesterone receptor (PR), and ERBB2 receptor (HER2)." (PMID 32397382, 2020). "Breast cancer (BC) can be histologically classified to luminal A, luminal B, Her2 positive, basal-like, and normal-like, with respect to the biomarkers status of estrogen receptor (ER), progesterone receptor (PR), and HER2." (PMID 32784928, 2020). "Recent investigations on rabbit mammary carcinomas analyzed in detail the histological features, estrogen and progesterone receptor status, as well as the intra-tumoral presence of retained non-neoplastic myoepithelial cells and tumor cells with a myoepithelial differentiation." (PMID 32824521, 2020). "Although information on protein half-life is limited, indirect information is obtained in studies performed with immunohistochemical markers for breast cancer, i.e., estrogen receptor (ER), progesterone receptor (PR), and human epidermal growth factor 2 (HER2)." (PMID 31264038, 2019). "Notably, the treatment of breast cancer patients is often based on immunohistochemical analysis of ER, progesterone receptor (PgR), Ki67, and HER2." (PMID 31354394, 2019). "Breast cancer is a highly heterogenic oncological disease initially classified into five intrinsic subtypes based solely on gene expression of estrogen receptors (ERs), progesterone receptor (PGR) and tyrosine kinase receptor HER2." (PMID 30858763, 2019). "Tumor factors previously known to predict breast cancer prognosis included in this study was tumor size, lymph node status, tumor grade, histological type, ER and PgR status, HER2 amplification, Ki67 expression, and molecular subtypes derived from the factors above." (PMID 31358030, 2019). "In clinical, breast cancer had been divided into five subtypes according to the expression patterns of estrogen receptor (ER), progesterone receptor (PR) and human epidermal growth factor receptor 2 (HER2), which was useful in predicting clinical outcome and selecting appropriate therapy." (PMID 30636640, 2019). "In this regard, we would like to shed light on the interaction between inflammation, as indicated by WBC count, and breast cancer burden according to estrogen receptor (ER) and progesterone receptor (PR) status in the context of body mass index and menopausal status." (PMID 30962496, 2019). "ERα, as well as its target PGR (PR), is an established biomarker in breast cancer patients." (PMID 30631046, 2019). "Furthermore, the efficacy of a progesterone receptor antagonist mifepristone (RU486) has been shown to be effective in preventing mammary tumors in BRCA1 null mice." (PMID 31771627, 2019).